ATP13A4 (ATPase 13A4)
Description:
Polyamine transporter mediating cellular uptake of putrescine, spermidine and spermine (Probable). May be involved in the regulation of intracellular calcium levels (By similarity).
Synonyms: DKFZp761I1011; FLJ37958
Tractability: Antibody: its Gene Ontology location is reachable by antibodies, with high confidence; UniProt predicts a signal peptide or a membrane-spanning region.
Gene: Protein-coding gene on chromosome 3 (193,398,967 to 193,593,111, reverse strand). Ensembl gene ENSG00000127249.
Subcellular location: Endoplasmic reticulum; Early endosome membrane; Late endosome membrane; Recycling endosome membrane
Pathways (Reactome):
Transport of small molecules: Ion transport by P-type ATPases
Gene Ontology:
Molecular function: ATPase-coupled monoatomic cation transmembrane transporter activity; polyamine transmembrane transporter activity; ABC-type polyamine transporter activity; ABC-type putrescine transporter activity; ATP binding; ATP hydrolysis activity; nucleotide binding; P-type ion transporter activity; P-type transmembrane transporter activity
Biological process: polyamine transmembrane transport; intracellular calcium ion homeostasis; monoatomic ion transmembrane transport; monoatomic cation transmembrane transport; putrescine transport
Cellular component: early endosome membrane; endoplasmic reticulum membrane; late endosome membrane; plasma membrane; recycling endosome membrane; endoplasmic reticulum; membrane
Genetic constraint (gnomAD): Loss-of-function variants: 106 observed, 139.05 expected, observed/expected ratio (o/e) 0.76, 90% interval 0.65 to 0.9. The upper end of that interval is the gene's LOEUF score, 0.9, which puts it in group 3 of 6, group 1 being the genes least tolerant of losing a copy. Missense variants: 1,322 observed, 1,432.5 expected, observed/expected ratio (o/e) 0.92, 90% interval 0.88 to 0.97. Synonymous variants: 459 observed, 507.32 expected, observed/expected ratio (o/e) 0.9, 90% interval 0.84 to 0.98.
Homologues: Orthologues: chimpanzee ATP13A4 (99% identical), macaque ATP13A4 (98% identical), pig ATP13A4 (92% identical), dog ATP13A4 (91% identical), guinea pig ATP13A4 (88% identical), mouse Atp13a4 (87% identical), rat Atp13a4 (87% identical), tropical clawed frog atp13a4 (63% identical), tropical clawed frog atp13a5l.2 (54% identical), tropical clawed frog atp13al (48% identical), Drosophila melanogaster anne (37% identical), Caenorhabditis elegans catp-6 (36% identical), and 10 more. Paralogues in human: ATP13A5 (59% identical), ATP13A3 (45% identical), ATP13A2 (39% identical), ATP13A1 (25% identical), ATP2A2 (17% identical), ATP2B3 (17% identical), ATP2B1 (17% identical), ATP2A3 (17% identical), ATP2B4 (17% identical), ATP2B2 (16% identical), ATP2A1 (16% identical), ATP1A1 (16% identical), and 9 more.
Diseases named in the same sentence as ATP13A4 in open-access papers:
ATP13A4 is named in the same sentence as 28 diseases in open-access papers, as found by Europe PMC text mining. Sharing a sentence is not in itself a finding about the gene and the disease. The quoted sentences say what the papers report.
ovarian carcinoma (3 papers, 2023 to 2025). A malignant neoplasm originating from the surface ovarian epithelium. "ATP13A4 amplification has been frequently observed in patients with non‐small‐cell lung cancer ovarian cancer, cervical cancer, head and neck cancer, endometrial cancer, uterine endometrioid carcinoma, bladder cancer, melanoma, and breast cancer." (PMID 39981745, 2025). "Of note, ATP13A4 underwent amplification in over 10% of patients with ovarian cancer, cervical cancer, head and neck cancer, endometrial cancer, uterine endometrioid carcinoma, bladder cancer, melanoma, lung cancer and breast cancer." (PMID 37371498, 2023).
autism spectrum disorder (2 papers, 2018 to 2021). A spectrum of developmental disorders that includes autism, and Asperger syndrome. "At least some P5B isoforms are of vital importance for the nervous system, since ATP13A2 and ATP13A4 are linked to respectively Parkinson disease and autism spectrum disorders." (PMID 29505581, 2018). "In addition, several individuals with autism spectrum disorders carried a mutation in the coding region of the ATP13A4 gene, substituting D646 for E646." (PMID 29505581, 2018).
breast carcinoma (2 papers, 2023 to 2025). "In conclusion, our findings shed light on ATP13A4 as a novel member of the enigmatic PTS that is implicated in the upregulated PTS in MCF7 breast cancer cells." (PMID 37371498, 2023). "Follow-up studies are required to investigate whether increased ATP13A4 expression is a general hallmark of breast cancer, or whether other polyamine transporters such as ATP13A2 and ATP13A3 may also be implicated." (PMID 37371498, 2023). "We also reported that high ATP13A4 expression explains the increased polyamine uptake in the breast cancer cell line MCF7 compared to the non‐tumorigenic epithelial breast cell line MCF10A." (PMID 39981745, 2025). "Our study is the first to characterize ATP13A4 as a polyamine transporter that plays a role in the PTS of MCF7 breast cancer cells." (PMID 37371498, 2023). "Besides a postulated physiological function in glandular tissue, ATP13A4 emerges as a polyamine transporter that is upregulated in MCF7 breast cancer cells, where it contributes to increased PTS activity." (PMID 37371498, 2023). "In contrast to the ubiquitously expressed ATP13A2-3 isoforms, ATP13A4 expression is tissue-specific and found mainly in epithelial glandular tissue such as the mammary glands, which fits well with a putative role in breast cancer." (PMID 37371498, 2023). "In this study, we present evidence that the elevated PTS in the commonly studied breast cancer cell line MCF7 may depend on the increased expression of ATP13A4, which we here establish as a novel polyamine transporter in the PTS that drives polyamine-dependent phenotypes in MCF7 breast cancer cells." (PMID 37371498, 2023). "Future in-depth characterization of both the cytosolic and organellar impacts of ATP13A4’s transport function will be instrumental in further understanding its role in (breast) cancer and may validate ATP13A4 as a candidate therapeutic target for anticancer drugs that block the PTS." (PMID 37371498, 2023). "In conclusion, we established ATP13A4 as a new polyamine transporter in the human PTS and showed that ATP13A4 may play a major role in the increased polyamine uptake of breast cancer cells." (PMID 37371498, 2023).
schizophrenia (2 papers, 2021 to 2023). A major psychotic disorder characterized by abnormalities in the perception or expression of reality. "Studies on families have revealed that ATP13A4 gene variants are associated with both schizophrenia and autism." (PMID 38020758, 2023). "ATPase type 13A4 (ATP13A4) gene (verbal and social interaction skills) expression was up-regulated in Broca’s area of schizophrenia." (PMID 34858129, 2021).
Cachexia (1 paper, 2022). Severe weight loss, wasting of muscle, loss of appetite, and general debility related to a chronic disease. "Of the six proteins that showed significant differences between the patients with and without cachexia, three were lower (CNPD1, APOA4, DACH1) while three were higher (BCL3 NARS2, ATP13A4) in cachexia." (PMID 36080280, 2022).
Hepatitis C (1 paper, 2024). "Interference with many signaling pathways, such as NOD-like receptor signaling pathway, Herpes simplex infection, Hepatitis C, PI3K-Akt signaling pathway, and many factors, such as Atp13A4 and Gbgt1, affect the proliferation and apoptosis of 3T3-L1 preadipocytes." (PMID 39123503, 2024).
lung adenocarcinoma (1 paper, 2023). A carcinoma that arises from the lung and is characterized by the presence of malignant glandular epithelial cells. "The first study found an association of ATP13A4 with high-grade serous ovarian carcinoma, while the second study linked ATP13A4 to lung adenocarcinoma through anaplastic lymphoma kinase (ALK) rearrangements." (PMID 37371498, 2023).
neuroblastoma (1 paper, 2025). Neuroblastoma (NB) is the most common solid, extracranial childhood tumor. "SLC3A2, ATP13A2, ATP13A3 are abundantly expressed in neuroblastoma tumors, while ATP13A4 and ATP13A5 expression is low." (PMID 39981745, 2025).
non-small cell lung carcinoma (1 paper, 2023). A group of at least three distinct histological types of lung cancer, including non-small cell squamous cell carcinoma, adenocarcinoma, and large cell carcinoma. "Patients with non-small-cell lung cancer showed the highest frequency of ATP13A4 alteration (>60%), with amplification as the primary genetic alteration type." (PMID 37371498, 2023).
cancer (1 paper, 2023). A tumor composed of atypical neoplastic, often pleomorphic cells that invade other tissues. "Many cancer types rely on an increased PTS, but it is unlikely that ATP13A4 is the only P5B-ATPase that is implicated in cancer." (PMID 37371498, 2023). "This is required to validate ATP13A4 as a candidate therapeutic target for the blocking of the PTS in specific cancer types." (PMID 37371498, 2023). "Our work provides a stepping stone to further establish the potential of ATP13A4 as a therapeutic candidate in cancer." (PMID 37371498, 2023). "Across cancers, the median overall survival time was significantly shorter for patients with ATP13A4 alterations (29.1 months versus 57.9 months for reference group)." (PMID 37371498, 2023). "To further explore the putative role of ATP13A4 in other cancer types, we investigated the prevalence of ATP13A4 genetic alterations across various human cancers using the online database cBioPortal in a pan-cancer dataset." (PMID 37371498, 2023). "In addition, future knockout experiments will be essential to further corroborate the contributing roles of ATP13A4 in the upregulation of the PTS in cancer cells." (PMID 37371498, 2023). "Thus far, two other studies have highlighted a role for ATP13A4 in human cancer." (PMID 37371498, 2023). "Altogether, these findings confirm that ATP13A4 alterations may be involved in cancer." (PMID 37371498, 2023). "The ATP13A4-mediated upregulation of the PTS sensitizes cells to polyamine cytotoxicity, which is a surprising finding, since cancer cell proliferation relies on elevated polyamine levels." (PMID 37371498, 2023).
neurological disorders (1 paper, 2018). "Also, the dysfunction of ATP13A2 and ATP13A4 are linked to various neurological disorders." (PMID 29505581, 2018).
ATP13A4 also shares sentences with these, for which no sentence is quoted: bladder cancer (2 papers); cervical cancer (2); endometrial cancer (2); head and neck cancer (2); melanoma (2); Sepsis (2); uterine endometrioid carcinoma (2); acute kidney injury (1); autism (1); epilepsy (1); Herpes simplex infection (1); lung carcinoma (1); Parkinson disease (1); psychiatric disorder (1); serous ovarian carcinoma (1); specific language impairment (1); tumor (1).